IGF1 (insulin like growth factor 1)
Diseases named in the same sentence as IGF1 in open-access papers (continued):
Sharing a sentence is not in itself a finding about the gene and the disease.
cardiovascular disease (continued). "Moreover, IGF-1 levels are generally inversely related to cardiovascular disease risk, because IGF-1 improves cardiovascular function and myocardial apoptosis, and is related to vascular endothelial function." (PMID 29758048, 2018). "However, the underlying mechanisms between IGF-1 deficiency and cardiovascular disease are poorly understood." (PMID 28806738, 2017). "Similarly, both very low and very high levels of IGF-1 have been associated with increased risk of mortality from cardiovascular disease or cancer." (PMID 28646237, 2017). "Furthermore, elevated levels of IGF-1 may be associated with certain diseases such as various types of cancers, certain cardiovascular diseases, and metabolic disorders." (PMID 38987734, 2024). "Interestingly, deficiencies in IGF-1 or growth hormone are associated with an increased risk of cardiovascular disease, yet centenarians tend to exhibit improved insulin sensitivity, low IGF-1 levels, and specific mutations in the insulin receptor that are associated with extreme longevity." (PMID 38203522, 2023). "However, underlying mechanisms between IGF-1 deficiency and cardiovascular disease remain elusive." (PMID 28806738, 2017). "Circulating IGF-1 has multifaceted antioxidant, anti-inflammatory, and antiapoptotic effects that alleviate the burden of cardiovascular disease in experimental models." (PMID 38428899, 2024). "Despite the increasing number of known miRNAs related to IGF-1, their role in cardiovascular disease, particularly MIRI, is poorly understood." (PMID 38428899, 2024). "The study has showed that the probability of cardiovascular disease in rodent model is significantly reduced when the level of serum IGF-1 is low." (PMID 37063954, 2023). "Increasing evidence has highlighted the cardioprotective effects of IGF-1 in the setting of cardiovascular disease." (PMID 36970368, 2023). "IGF1 also exerts critical effects in endothelial-protective, anti-platelet and anti-thrombotic activities in cardiovascular disease." (PMID 37465678, 2023). "IGF-1 levels negatively correlate with body weight (BW) and age, and this additionally confounds examination of the role of IGF-1 in cardiovascular disease." (PMID 36602878, 2023). "In recent years, the important role of IGF-1 in the occurrence and development of cardiovascular diseases has attracted increasing attention." (PMID 34621793, 2021). "Furthermore, insulin-like growth factor I (IGF-1) regulates contractility, metabolism, hypertrophy, autophagy, senescence, and apoptosis in the heart and its deficiency in humans and animal models has been associated with an elevated risk of cardiovascular disorders." (PMID 32391340, 2020). "Epidemiological evidence for a bidirectional link between serum IGF-1 concentrations and cardiovascular disease (CVD) has been repeatedly demonstrated." (PMID 33633687, 2020). "In the case of APOE, APOE ε2 isoform decrease the risk of cardiovascular disease and APOE ε4 isoform limits longevity and FOXO3 is linked to insulin/insulin-like growth factor 1 (IGF1) signaling." (PMID 30926763, 2019). "It is well documented that the cardiovascular system is an important target organ for growth hormone (GH) and insulin-like growth factor (IGF)-1 in humans, and GH /IGF-1 deficiency significantly increases the risk for cardiovascular diseases (CVD)." (PMID 29375617, 2017). "A decrease in IGF-1 has been reported with increased age, and also in advanced cardiovascular disease." (PMID 28609475, 2017). "We identified several important pathways for cardiovascular disease, such as insulin, IGF1 and glucose signaling pathways, TGF-β pathway, as well as hypoxic and oxygen homeostasis regulation of HIF-1-α (and for a complete list)." (PMID 27317124, 2016). "A general finding is that obese patients fulfilling criteria for MetS together with low IGF-1 plasma levels tend to develop a worse cardiovascular disease outcome than those with mid-normal to high-normal IGF-1 levels." (PMID 26733412, 2016).
cardiovascular disease (continued). "IGF-1 can regulate cell metabolism and promote its growth and development, in recent years, as a key regulator of cardiovascular disease; IGF-1 is gradually valued." (PMID 26844226, 2015). "A general finding is that obese patients that fulfill the criteria for MetS presenting low IGF-1 plasma levels, tend to develop a worse cardiovascular disease outcome than those with mid-normal to high-normal IGF-1 level." (PMID 26467524, 2015). "IGF1 is a well-documented gene that plays a role in cardiovascular disorders and metabolic disorders." (PMID 22479346, 2012). "This increased susceptibility in males may stem from diminished free testosterone levels, suboptimal physical activity, a higher prevalence of cardiovascular disease, and suboptimal insulin-like growth factor-1 levels." (PMID 38281041, 2024). "There is ongoing debate on the role of IGF-1 in cardiovascular disease." (PMID 36602878, 2023). "Correlations between IGF1 concentration and magnesium and lipids could be used as biomarkers for early diagnosis of cardiovascular disease." (PMID 35395053, 2022). "IGF-1 plays an important role both in homeostasis and cardiovascular disease." (PMID 36361979, 2022). "In addition, some studies revealed that some cellular pathways (e.g., the insulin-like growth factor 1/PI3K/Akt pathway and nitric oxide signaling pathway) and molecular mechanisms were associated with the positive effect of PA on cardiovascular disease." (PMID 36466532, 2022). "IGF-1 increased significantly in our high-protein, omega-3-enriched group, which is in line with another observation after eight weeks of omega-3 supplementation in 62 middle-aged men with cardiovascular disease." (PMID 36296958, 2022). "Platelet hyperactivity promotes the pathogenesis of cardiovascular disease and may be affected by elevated levels of circulating growth factors, which include insulin-like growth factor-1 (IGF-1)." (PMID 33121005, 2020). "Increasing evidences suggest that IGF-1 has a protective effect on cardiovascular disease." (PMID 26844226, 2015). "Moreover, IGF-1 also plays a role in cardiovascular disease." (PMID 41169887, 2025). "As such, the roles of IGF-1 in cardiovascular disease remain unclear and warrant further study." (PMID 36970368, 2023). "Excess production of growth hormone (GH) and insulin-like growth factor 1 (IGF-1) can result in symptoms such as changes in appearance and enlargement of hands and feet, as well as fatigue, joint pain, and systemic complications including cardiovascular disease and respiratory disease." (PMID 33790860, 2021). "Regarding IGF-1, this cytokine plays major a role in the main pathways in the progression of metabolic traits, such as progression of T2DM complications, as CKD, and the development of cardiovascular disease." (PMID 35205271, 2022). "Our findings for IGF-1 levels and cardiovascular disease corroborate those of some but not all observational studies." (PMID 32548700, 2020). "On the contrary, the osteogenic factors insulin-like growth factor-1 (IGF-1), FGF-2 and Follistatin-related protein 1 released after exercise, improve endothelial function of vascular system, with a significant relevance of physical activity in cardiovascular disease." (PMID 34554363, 2022). "Cats with confirmed hypersomatotropism (IGF-1>1000ng/ml and pituitary mass; n = 67) were prospectively recruited, as were two control groups: diabetics (IGF-1<800ng/ml; n = 24) and healthy cats without known endocrinopathy or cardiovascular disease (n = 16)." (PMID 29596445, 2018).
metabolic disorders (122 papers, 2010 to 2026). "WT and Sarm1KO mice develop comparable T1D-associated metabolic disease, suppression of IGF-1, and muscle atrophy." (PMID 38175722, 2024). "The alteration of IGF-1 is not only associated with short stature but is also implicated in inflammation, neurological disorders, metabolic diseases, and aging (it declines after the third decade)." (PMID 36292632, 2022). "At present, there is no definitive evidence of the interaction between the circadian clock system and the GH/IGF-1 axis and the pathophysiological mechanism causing metabolic disorders." (PMID 34566581, 2021). "The metabolic and hepatic response to exogenous leptin treatment was associated with several factors, including the severity of metabolic disease at baseline, levels of triglycerides and triglyceride-rich apolipoproteins, baseline leptin levels, and changes in IGF-1 levels." (PMID 40520449, 2025). "The lack of growth hormone in adults and, as a result, severe deficiency of IGF1 may be the basis of the current metabolic disorders, reduced quality of life, and musculoskeletal diseases." (PMID 39980897, 2025). "As SGA-FOF have higher IGF-1 level, they may have a higher risk for cardiovascular and metabolic disease in later life, making breastfeeding the optimal choice of feeding for all infants." (PMID 35105325, 2022). "The role of IGF-1 needs further examination whether it is a potential therapeutic target in obese patients of increased cardiometabolic risk or only an indicator of metabolic disorders." (PMID 34485526, 2021). "Evidence on IGF-1 in relation to metabolic diseases is still controversial, i.e. low levels of IGF-1 have been suggested to have beneficial effects on glucose homeostasis and may also sensitise insulin actions, thereby decreasing metabolic disease risk." (PMID 29618342, 2018). "Adult GH absence and the consequent severe IGF1 deficiency may underlie the patient's present metabolic disorders, osteomuscular symptoms, and reduced quality of life." (PMID 24683479, 2014). "Therefore, GH/IGF-1 deficiency is the primary causative factor for metabolic disorders in AGHD." (PMID 39610397, 2024). "Notably, as metabolic disorders are frequently associated with low IGF-1 levels in subjects with MetS, it could be hypothesized that IGF-1 is probably not involved as a proliferation inducer but might have other autocrine and/or paracrine actions." (PMID 37106164, 2023). "Thus, low IGF-1 levels may be an important marker of adiposity-associated metabolic disorders in obese patients." (PMID 36418379, 2022). "Previous studies have reported that reduced levels of IGF-1 in the blood of patients with metabolic disorders are a common feature." (PMID 38473814, 2024). "Recently, as the incidence of dementia accompanying metabolic disorders increases, the interest in the effects of IGF-1, which exhibits various ameliorating effects in metabolic disorders, on the central nervous system (CNS) is increasing." (PMID 38473814, 2024). "Although overdose of IGF‐1 leads to inflammatory reaction and metabolic disorder, an appropriate amount thereof is essential for scavenging intracellular ROS and maintaining cellular mitochondrial biogenesis." (PMID 37042047, 2023). "IGF-1 levels are reportedly low in a variety of metabolic diseases and are believed to be involved in OSAHS progression." (PMID 36120463, 2022). "We should be cautious in interpreting and managing IGF-1 levels, as a parameter for evaluating the risks of metabolic disorders, in obese subjects." (PMID 36418379, 2022). "NobiletinNOB effectively reversed glucolipid metabolism disorders triggered by PA by increasing the insulin/IGF-1 signaling pathway and regulating key enzymes of de novo lipogenesis." (PMID 31408938, 2019). "In this review, we have summarized recent progresses on the links between aging and metabolic diseases, focusing on key signaling pathways such as the insulin/IGF-1 and their tissue specific function in aging." (PMID 24474199, 2014).
metabolic disorders (continued). "There was no statistical relation between SNHL and the clinical-laboratory parameters analyzed, including disease duration, mean age, disease activity, metabolical disorders, GH and IGF-1 levels." (PMID 22936144, 2012). "Several factors appear to be related to the hepatic and/or metabolic response to exogenous leptin treatment, including the severity of metabolic disease at baseline, levels of triglycerides and triglyceride-rich apolipoproteins, baseline leptin levels, and changes in IGF-1 levels." (PMID 40520449, 2025). "Most of these studies have focused on older populations or metabolic diseases, and no studies have explored the association of IGF-1 and IGBP-3 with metabolic abnormalities assessed by clinical parameters among children and adolescents." (PMID 40538800, 2025). "Endocrine and metabolic disorders: All children received GH treatment at the same recommended dose, and median IGF-1 levels were in the normal range with significantly higher values in the OT-exposed group compared to the non-exposed group (198 ng/mL vs. 132 ng/mL, p = 0.01)." (PMID 40025514, 2025). "However, the intricate relationship between GH/IGF-1 and metabolic disorders necessitates further investigation to comprehensively elucidate the underlying mechanisms linking these hormones to the development of metabolic syndrome." (PMID 39610397, 2024). "The results indicate that dysregulation of GH and IGF-1 may disrupt serum asprosin levels, potentially contributing to the development of metabolic disorders." (PMID 39610397, 2024). "Prospective studies would provide more conclusive and long-term additional validation (e.g. more precise examination of time-courses of IGF-1 levels might herald future-increases in adiposity and the onsets of metabolic disorders)." (PMID 36418379, 2022). "Thus, multiple comorbidities involving metabolic disorders are important clinical characteristics of obese patients with low IGF-1 levels." (PMID 36418379, 2022). "Further, we have determined that glucocorticoid exposure during this window of development results in dysregulation of insulin and IGF1 signaling and an adaptive immune response in the TE, suggesting the potential development of altered placental capacity and metabolic disease later in life." (PMID 35948369, 2022). "IRS-1 and PI3K are essential for insulin signaling and action as well, thus suggesting that dysregulations of IGF-1 protein circulating levels may have a role in metabolic diseases." (PMID 30469501, 2018). "Given that PCOS is a reproductive and metabolic disorder, factors produced by the liver that could affect ovarian function as well as metabolism, namely IGF1 and its signaling system, were also studied." (PMID 21935484, 2011). "Substantial heterogeneity across studies may reflect differences in study design, population characteristics, timing of IGF-1 measurement, laboratory assays, and inconsistent adjustments for confounding factors such as age, metabolic disorders, and circulating IGFBPs." (PMID 41586110, 2025). "Given the role of IGF-1 in metabolic regulation, we hypothesize that improvements in insulin sensitivity and liver histopathology following exogenous leptin therapy would be associated with changes in IGF-1 levels, which may correlate with improvements in metabolic disease." (PMID 40520449, 2025). "Our findings delineate a mechanism in which LLPS of IRS-1-mediated signalosomes serves as an organizing center for insulin/IGF-1 signaling and implicate the role of aberrant IRS-1 LLPS in metabolic diseases." (PMID 35764611, 2022). "In brain, palmitate-induced CHOP activation decreases insulin-like growth factor 1 (IGF1) and leptin expression in vitro and in vivo; these two peptide hormones have essential implications in a variety of metabolic diseases." (PMID 29921793, 2018).
metabolic disorders (continued). "As shown by microarray analyses, mRNA levels of the Wnt/β‐catenin signalling target genes related to metabolic diseases, including TCF7L2, WISP‐1, IGF‐1 and PPARδ, were lower in the visceral adipose tissues from patients with T2DM than in tissues from non‐diabetic subjects." (PMID 35384342, 2022). "Most serum IGF-1 tend to interact with IGFBP-3, which is also transactivated by GH, indicating that crosstalk between GH and IGF-1 is interconnected and responsible for host growth, and regulation of metabolic disorders." (PMID 34681914, 2021). "In the context of metabolic disorders, studies suggest that melatonin restores the activity of the PI3K/AKT/mechanistic target of rapamycin (mTOR) pathway, reduces insulin receptor substrate-1 (IRS-1) phosphorylation, and increases insulin-like growth factor 1 (IGF-1) activity." (PMID 40722923, 2025). "Studies confirmed that blood IGF1 levels decreased in fetuses with IUGR in mammals, and these levels were significantly higher in IUGR offspring exhibiting “catch-up growth” than in those not exhibiting “catch-up growth”, which is related to adult metabolic diseases." (PMID 37978540, 2023).